S100P (S100 calcium binding protein P)
Diseases named in the same sentence as S100P in open-access papers (continued):
Sharing a sentence is not in itself a finding about the gene and the disease.
tumor (continued). "But while no visible liver metastases were observed for the control group, an average of three liver metastases with a size above 1 mm in diameter were counted in animals with S100P-overexpressing tumours (P< 0.0001)." (PMID 35597866, 2022). "In contrast, mEPCs from CC1 and GBC11 displayed upregulation of multiple tumor-specific genes (e.g., S100P, TSPAN1, CEACAM5)." (PMID 36198671, 2022). "Average metastasis-free survival of patients drops from 48.7 months (±3.5; 95% CI = 41.8–55.6) to 28.0 months (±4.1; 95% CI = 19.9–36.0) when S100P is highly expressed in the primary tumour." (PMID 35597866, 2022). "In contrast, we observed high MACC1 and elevated S100P IHC staining in tumour sections from CRC patients who suffered from metachronous metastasis." (PMID 35597866, 2022). "S100P showed high expression in tumor tissues, but patients with low expression of S100P survived longer, which were consistent with the data from TGGA." (PMID 34805160, 2021). "S100P, a calcium-binding protein, can advance tumor progression and metastasis in pancreatic and several other cancers." (PMID 33842379, 2021). "Cells expressing wild-type S100P exhibited high incidences of metastasis, with 70% (cell clone) and 75% (cell pool) of tumour-bearing rats exhibiting lung metastases, similar to those reported previously." (PMID 34680103, 2021). "Although the authors did not interrogate RAGE signaling pathways in their study, it is probable that the effect of S100P on cell migration, tumor growth, and metastasis was partially mediated by RAGE." (PMID 34360919, 2021). "Consistent with this, we analyzed the TCGA and GEPIA databases and found that S100P was highly expressed in LUAD tumor tissues, and was significantly negatively correlated with patient survival." (PMID 34805160, 2021). "On the contrary, S100P was highly expressed in tumor tissues, and patients with low expression of S100P survived longer." (PMID 34805160, 2021). "In this study, we identified S100P as a driver gene for tumor cells to recruit and polarize TAMs, a critical TIC subset for immunosuppressive tumor niche formation." (PMID 34805160, 2021). "An anti-S100P monoclonal antibody can sabotage these activities and significantly delay liver metastasis and tumor growth." (PMID 34527585, 2021). "S100P directly stimulates tumor cell growth, movement, and invasion; protects PC cells from apoptosis or anoikis caused by chemotherapy drugs; or mediates changes in the cytoskeleton of carcinoma cells, thereby promoting growth, survival, and invasion of PC." (PMID 34527585, 2021). "Similar to these results, our findings showed that the expression of S100P was significantly upregulated in HCC tissues than in para-tumor tissues." (PMID 33815482, 2021). "A cromolyn analog which inhibits S100P was used in pancreatic cell line and mice models to reduce tumor growth and metastasis." (PMID 34239729, 2021). "Overall, in this study, we identified circ_0092314, as a novel oncogenic circRNA induces EMT and invasion of PAAD cells via elevating the abundance of S100P by sponging a tumor suppressor miR-671." (PMID 33842379, 2021). "It was found that S100P gene expression was localized on cancer cells and higher in tumor than in paracancerous tissues." (PMID 34805160, 2021). "S100P is expressed in various normal and tumor tissues and is involved in diverse biological functions." (PMID 34200172, 2021). "The gene expression profile analysis demonstrated that the levels of S100A4/S100A6/S100A10/S100A11/S100A13/S100P were higher in tumor than in normal liver samples." (PMID 33815482, 2021). "S100P is expressed in several healthy tissues, including the lungs, heart, kidneys, and bone marrow, as well as in tumor tissues, including those of pancreatic and breast cancers." (PMID 34200172, 2021). "S100P is highly expressed in a variety of tumor cells and is a biomarker for early diagnosis of tumors." (PMID 34805160, 2021).
tumor (continued). "A recent study showed that S100P played an important function during hypoxia by promoting cell migration and tumor metastasis in hepatocarcinoma cells and tumors." (PMID 34360919, 2021). "In tumors, S100P was found to promote tumor cell proliferation and survival, as well as metastasis through its interaction with RAGE." (PMID 34360919, 2021). "In tumor tissues, S100P was negatively correlated with M1 macrophages (p = 0.012) and positively with M2 macrophages (p = 0.033)." (PMID 34805160, 2021). "Examples of immunocytochemical staining of the tumours and metastases arising from injection into the mammary fat pads of syngeneic rats of Rama 37 cells expressing wild-type S100P have been published previously." (PMID 34680103, 2021). "S100P, a calcium-binding protein, is known to advance tumor progression and metastasis in pancreatic and several other cancers." (PMID 32707527, 2020). "S100P can be localized inside cells or be secreted in the extracellular space; both intracellular and extracellular S100P have been incriminated in tumor proliferation and metastasis." (PMID 33256110, 2020). "•Virtual screening identified hits against S100P, a protein target involved in tumor progression and metastasis." (PMID 32707527, 2020). "The protein accumulation of S100P at tumor sites also stimulates tumor invasion by inducing angiogenesis." (PMID 33042844, 2020). "S100P has recently attracted great attention due to its implication in malignant transformation and tumor progression, and in predicting prognosis and metastasis in several cancer types." (PMID 33042844, 2020). "This is confirmed in neoadjuvant chemotherapy patients that the expression level of S100P in HER2+ tumor tissues decreases significantly after chemotherapy compared with pre-chemotherapy." (PMID 33042844, 2020). "Among these, COL17A1, ITGB6, LAMC2, and S100P were upregulated in tumor tissues, whereas only CHGA was downregulated." (PMID 33015155, 2020). "Subsequent virtual screening of lead-like databases identified hits – structurally distinct from cromolyn – that show promise as inhibitors of S100P’s tumor-promoting mechanisms and therefore potentially as chemotherapeutic agents for PDAC." (PMID 32707527, 2020). "S100P not only promotes tumor progression and metastasis, but also plays a role in drug responses to chemotherapy, endocrine therapy, and targeted therapy." (PMID 33042844, 2020). "This revealed that the expression levels of S100P in tumor tissue decreased by 46.55% after chemotherapy, compared with before chemotherapy (p = 0.015)." (PMID 33042844, 2020). "High S100P expression is observed in several types of cancers and has been shown to mediate tumor growth, drug resistance, and metastasis." (PMID 31303963, 2019). "We postulated environmental factor-related inflammation such as OV infection and tumor-producing inflammation such as hypoxia and S100P-RAGE in the multiple steps of carcinogenesis." (PMID 30402042, 2018). "Over-expression of S100P in HCC and other tumor tissues were observed and S100P was reported to be a prognostic factor for HCC early recurrence." (PMID 27216119, 2016). "S100P is a marker closely connected to tumor growth, migration and invasion, which indeed would have an additional and beneficial functionality in cancer defense." (PMID 27240402, 2016). "Ever since it has been proven that S100P is able to promote tumour invasion and formation of metastases." (PMID 26880885, 2016). "Less is known about the inflammatory effects of S100P, which has been shown to mediate tumor growth, drug resistance and metastasis through RAGE binding on cancer cells." (PMID 26751474, 2016).
tumor (continued). "Hua KT and his colleagues demonstrated that Keap1 functions as a suppressor of tumor metastasis by targeting the Nrf2/S100P pathway in non‐small‐cell lung cancer cells." (PMID 27650414, 2016). "This study aimed at better understanding of the role of S100P protein in the response of tumor cells to cytotoxic therapy." (PMID 26967060, 2016). "S100P levels in the tumor region were elevated when compared to normal regions in 54.2% (13/24) of specimens." (PMID 26320193, 2015). "Convincing evidence has shown that S100P expression is found in a variety of cancers and appears to be correlated with the invasion and metastatic process of tumor cells." (PMID 25780527, 2015). "For verification, qPCR analysis revealed that S100P mRNA expression was detected in both types of tumor and their matched normal mucosa samples." (PMID 25585623, 2015). "In conclusion, our results suggest that SOX9 promotes tumor metastasis and invasion through regulation of S100P expression." (PMID 26009899, 2015). "Among all the potential dysregulated genes in both tumor types, S100P, a member of the S100 family of proteins containing 2 EF-hand calcium-binding motifs, was found to be upregulated and preferentially associated with polypoid CRC." (PMID 25585623, 2015). "The ligation of RAGE by S100P leads to cell proliferation and survival to mediate tumor development." (PMID 25084534, 2014). "We found that S100P expression correlated with high tumor grade, high serum AFP level (>200 ng/mL), and large tumor size (>5cm)." (PMID 23785431, 2013). "Patients with HCC tumors that expressed S100P were more likely to have early tumor recurrence (ETR) (P = 0.0189) and lower 5-year survival (P = 0.0023)." (PMID 23785431, 2013). "We also showed that S100P protein immunoreactivity was more intense at the tumor border, and that it was more diffuse and intense in satellite nodules and portal vein tumor emboli than in the main tumor mass." (PMID 23785431, 2013). "Because tumor stage and ETR are most important predictive factors for poor prognosis in HCC, we further analyzed the prognostic role of S100P expression in patients with high tumor stage or ETR." (PMID 23785431, 2013). "In cells that exhibited heterogeneous to focal or trace S100P expression, S100P was predominantly expressed at the periphery of the tumor masses and satellite nodules." (PMID 23785431, 2013). "The combinatorial analysis showed that HCC patients with high tumor stage and S100P expression had a significantly lower -5-year survival rate than high-tumor-stage HCC patients without S100P expression (P = 0.0026)." (PMID 23785431, 2013). "S100P expression closely correlated with high tumor grade (grade 2 to 4; OR, 2.12; 95% CI, 1.25–3.62; P = 0.0029) and high tumor stage (stages II and III; OR, 1.65; 95% CI, 1.02–2.69; P = 0.0319)." (PMID 23785431, 2013). "We found that S100P expression is an independent prognostic factor in HCC patients with high tumor stage and ETR." (PMID 23785431, 2013). "Very few studies have so far analyzed S100P expression in HCC, despite its well-known association with a variety of neoplastic diseases." (PMID 23166536, 2012). "In immunostained tumor tissues, AD cells showed immunostaining of S100P in the cytoplasm and the nucleus, while SQ cells showed immunostaining of RAB25 in the cytoplasm." (PMID 20142997, 2010). "S100P is a Ca2+ binding protein overexpressed in a variety of cancers, and thus, has been considered a potential tumor biomarker." (PMID 18282279, 2008). "S100P protein has been recently considered a potential biomarker of cancer due to its frequent expression in different types of tumor tissues." (PMID 18282279, 2008). "Our present results using a newly generated monoclonal S100P antibody confirmed the expression of S100P protein in several tumor categories." (PMID 18282279, 2008).
tumor (continued). "In the present study, we used a newly generated anti-S100P monoclonal antibody 18-9 for immunohistochemical analysis of S100P expression in a series of normal and tumor human tissues." (PMID 18282279, 2008). "Recently, it has been shown that S100P can induce anchorage-independence of tumor cells in vitro and improve tumor growth in a xenograft model." (PMID 18282279, 2008). "Among these genes, calcium-binding protein S100P has been found to be highly expressed in cells which develop acquired resistance to anti-tumor agents." (PMID 15656911, 2005). "Moreover, tumor-associated macrophages (TAMs) and myeloid-derived suppressor cells (MDSCs) are recruited and polarized by S100A8/A9 and S100P, reinforcing an immunosuppressive milieu that limits cytotoxic T cell infiltration." (PMID 41404073, 2025). "High S100P expression suppressed dendritic cell and mast cell abundance while promoting M0 macrophage infiltration, contributing to an immunosuppressive environment conducive to tumor progression." (PMID 40224483, 2025). "For instance, the immunosuppressive role of S100P suggests that its inhibition could synergize with immune checkpoint blockade to improve anti-tumor immunity." (PMID 41404073, 2025). "High S100P expression was significantly associated with tumor size (p = 0.001) but not with sex, age, T stage, N stage, M stage, or TNM stage." (PMID 41301873, 2025). "S100P also contributes significantly to tumor invasion and metastasis." (PMID 41404073, 2025). "Furthermore, a single-cell transcriptomic analysis involving 14 pairs of iCCA tumors and non-tumor liver tissues classified iCCA into two subtypes according to the expression of S100P and SPP1." (PMID 38339060, 2024). "The authors suggested that the high expression level of S100P in tumor tissues could serve as a potential target marker for diagnostic applications." (PMID 39284282, 2024). "RBMS1 ablation inhibits the translation of S100P and suppresses tumor metastasis." (PMID 38342601, 2024). "Tumor-infiltrating immune cells are stimulated by S100P through the activation of the receptor for advanced glycation end products, and this molecule could serve as a promising biomarker for immunosuppressive microenvironment." (PMID 39720723, 2024). "However, correlations were observed between S100A2 and S100A7 (R = 0.48), S100A11 (R = 0.54), S100A14 (R = 0.50), S10016 (R = 0.61) and S100P (R = 0.85), when comparing transcript levels from the tumor array." (PMID 37627239, 2023). "Monitoring of S100P levels may also be a useful predictor of tumor response to treatment with the experimental drug QN-302." (PMID 36985425, 2023). "However, the positive cells of NCAM1 (2.36%) and CDH2 (31.86%) accounted for a very low proportion of the total tumor cells in these seven S100P- iCCAs." (PMID 35347134, 2022). "Notably, S100P + cells accounted for 91.14% of total tumor cells from these seven iCCAs and displayed more representative and extensive-expression compared with the other markers (MUC5AC: 42.37%, and MUC6: 22.97%)." (PMID 35347134, 2022). "In addition, the interaction between Keap1 and Nrf2 was found to suppress LUAD tumor progression by inhibiting the S100P protein." (PMID 36177001, 2022). "Moreover, silencing of S100P significantly inhibited growth of 22Rv1 cells, while overexpressing S100P in PC3 cells resulted in increased proliferation of tumor cells." (PMID 35747825, 2022). "Thus, S100P can be used as a prognostic biomarker for metachronous metastasis of CRC tumour Stages II and III, and although correlated with the expression of MACC1, their combination further refines the determination of the metastatic risk of CRC patients." (PMID 35597866, 2022). "As CRC patients with CRC tumours of the UICC Stages II–III have a higher risk of distant recurrence, we specifically analysed this subgroup of tumour samples and indeed found a significant increase of S100P expression in tumours of patients with metachronous metastasis (P < 0.05; N = 43)." (PMID 35597866, 2022).
tumor (continued). "The discovery of an S100P-induced tumor immunosuppressive niche may provide a new understanding for targeted therapy based on S100P." (PMID 34805160, 2021). "Interestingly, we found that high expression of S100P was restricted to tumor cells, and along the direction adjacent to the cancer nest, S100P positive tumor cells and M2 macrophages significantly increased, while M1 macrophages significantly decreased." (PMID 34805160, 2021). "S100P, as an immune-associated gene (IAG) signature, can potentially be used in risk score models to predict the overall survival, stage, lymph node accumulation, tumor metastasis, B cells, and dendritic cell infiltration of lung adenocarcinoma." (PMID 34239729, 2021). "In PDAC, S100P is expressed in precursor lesions and is involved with tumor growth and invasion." (PMID 32005189, 2020). "Although it can be appreciated that S100P will be higher in high grade tumours due to increased cell proliferation, that observation was not made in this present study and could potentially be due to low sample size." (PMID 33238953, 2020). "In conclusion, S100P is only expressed in malignant tissues that result in EMT by activating MAPK/ERK1/2 and S100P accumulation that initiates NF-κB activation and AP-1–dependent oncogenic mi-RNA activation, which altogether enhanced tumor migration and invasion." (PMID 33117687, 2020). "Studies have shown that S100P overexpressing Panc-1 cells grew five-fold larger subcutaneous tumors than controls and that inhibition of the S100P/RAGE interaction could inhibit tumor growth." (PMID 33086527, 2020). "Further functional studies revealed that knockdown of S100P in wild-type E-cadherin GC cells impaired cell-cell adhesion and promoted both cell’s invasive capacity and sphere formation ability, indicating that S100P interferes with the adhesive and tumour suppressive functions of E-cadherin." (PMID 31767037, 2019). "In the present study, S100P gene expression and protein levels were significantly higher in resistant tumours after long-term treatment, as well as being differentially expressed before treatment, supporting its potential role as a therapeutic target and a predictive marker." (PMID 30616553, 2019). "Thereby, the S100P protein may contribute to the outgrowth of aggressive tumor cells resistant to cytotoxic therapy and promote cancer progression." (PMID 26967060, 2016). "Furthermore data revealed a relationship between treatment of CD133+ cancer cells with anti-CD3/anti-CD133 bispecific antibody-Cytokine Induced Killer (CIK) cells and S100P downregulation in the targeted tumor cells." (PMID 27240402, 2016). "It has been shown that Keap1 could inhibit tumor metastasis by targeting Nrf2/S100P pathway in NSCLC cells." (PMID 27579312, 2016). "Moreover, other representatives of the S100 family such as S100A4 and S100P were shown to be overexpressed in CCA tumor samples and were associated with increased tumor invasiveness." (PMID 27709523, 2016). "Elevated expression of S100P has been detected in several tumor types and suggested to be responsible for tumor metastasis and invasion, but the upstream regulatory mechanisms promoting S100P overexpression are largely unknown." (PMID 26009899, 2015). "However, xenografted tumor growth was suppressed in mice injected with HCT116-SOX9(+)/S100P(−) cells compared to HCT116-SOX9(+) cells (P = 0.005)." (PMID 26009899, 2015). "HCC with the β-catenin mutation but negative for S100P expression had lowest risk of high-stage tumor and ETR (21%, P = 0.0000446 and 12%, P = 0.00142, respectively)." (PMID 23785431, 2013).